XIST (X inactive specific transcript)
Diseases named in the same sentence as XIST in open-access papers (continued):
Sharing a sentence is not in itself a finding about the gene and the disease.
cardiac hypertrophy (9 papers, 2019 to 2023). "XIST promoted the progression of cardiac hypertrophy through competitively binding with miR-101 to enhance the expression of TLR2." (PMID 35990977, 2022). "Moreover, XIST acted as a sponge for miR-101 to aggravate cardiac hypertrophy in mice with transverse aortic constriction." (PMID 37226251, 2023). "The results disclosed that XIST, MALAT1 and H19 possibly regulated other miRNAs involved in cardiac hypertrophy, such as miR-15b, miR-19b and miR-29b in our research." (PMID 34362365, 2021). "LncRNA XIST was only differentially expressed in EPI-treated samples and could promote the progression of cardiac hypertrophy resulting in heart failure disease." (PMID 35415316, 2022).
colon cancer (9 papers, 2019 to 2023). "Following the combined decitabine/PBA treatment of colon cancer cells, we observed a highly significant sixfold induced expression of XIST and a three- and twofold induction, respectively, of its target genes NDRG1 and SEMA6A." (PMID 37208732, 2023). "This study has also confirmed the significance of XIST/miR-497-5p/FOXK1 in the pathogenesis of colon cancer." (PMID 34179019, 2021). "Another study in colon cancer cells has demonstrated over-expression of XIST and FOXK1, while down-regulation of miR-497-5p." (PMID 34179019, 2021). "LncRNA XIST expression is increased in colon cancer tissues, while XIST silencing inhibits colon cancer cell growth and reduces tumor growth in vivo." (PMID 33246471, 2020). "used qRT-PCR to measure the expression of lncRNA XIST in colon cancer tissues as well as in adjacent normal tissues, and showed that XIST expression is upregulated remarkably in tissues of colon cancer, thus indicating that XIST plays an oncogenic role in colon cancer." (PMID 37614816, 2023). "Similarly, knockdowns of PVT1, colon cancer-associated transcript 1 (CCAT1), and X-inactive specific transcript (XIST) in 5-FU-resistant colon cancer cells have also resulted in the successful restoration of 5-FU sensitivity." (PMID 34571731, 2021). "Expression of XIST has been increased in colon cancer cells." (PMID 34179019, 2021). "In colon cancer, METL14 downregulates the expression of lncRNA XIST by regulating the m6A level of XIST, thereby inhibiting the proliferation and metastasis of cancer cells." (PMID 36105111, 2022). "XIST also affects expression of β-catenin, cyclinD1, c-Myc, and MMP-7 in colon cancer cells." (PMID 34179019, 2021). "Moreover, we demonstrated XIST and its targets NDRG1 and SEMA6A to be significantly repressed in clinical samples (Fig. 5B2) and provided evidence for hypermethylation of NDRG1 and SEMA6A in colon cancer clinical samples (Fig. 5B3)." (PMID 37208732, 2023).
Down syndrome (8 papers, 2013 to 2025). "For example, XIST transgenics has gained interest as a possible therapeutic tool for chromosome dosage disorders, such as Down syndrome." (PMID 39140247, 2024). "We previously demonstrated that an integrated XIST transgene can broadly repress one chromosome 21 in Down syndrome (DS) pluripotent cells." (PMID 30518921, 2018). "Similarly in humans, the X chromosome also has a higher density of LINEs than chromosome 21, suggesting that additional factors such as small chromosome size may have contributed to the high-efficiency of XIST-mediated silencing in the Down syndrome model." (PMID 34222260, 2021).
seminoma (8 papers, 2019 to 2025). A radiosensitive malignant germ cell tumor found in the testis (especially undescended), and extragonadal sites (anterior mediastinum and pineal gland). "Seminomas predominantly maintain chromosome X silencing through persistent XIST expression, reflecting a primordial germ cell-like epigenetic state that directly contributes to elevated replication stress." (PMID 40568177, 2025). "Seminomas showed a significantly higher content of demethylated XIST as compared to non-seminomas." (PMID 31533343, 2019). "This difference may reflect subtype-specific strategies for managing extra X chromosome copies, with seminomas potentially relying more on constitutive XIST-driven for chromosome X silencing, whereas non-seminomas may modulate XIST expression according to the extent of chromosome X amplification." (PMID 40568177, 2025). "Notably, a significant association between the number of chromosome X copies and XIST expression was detected specifically in non-seminomas (linear regression adjusted tumor purity, P=4.63e-04), but not in seminomas (P=0.14)." (PMID 40568177, 2025). "A significant negative correlation was observed between XIST expression and DNA methylation levels on chromosome X in both subtypes (Pearson correlation; seminomas: R = −0.49, P = 1e-04; non-seminomas: R = −0.48, P = 8.1e-05)." (PMID 40568177, 2025). "Seminomas consistently exhibited elevated XIST expression, while non-seminomas showed greater variability (Seminomas vs. non-seminomas, linear regression adjusted tumor purity, P=3.81e-07)." (PMID 40568177, 2025). "In particular, the demethylation of XIST 5′ is augmented in seminomas compared to non-seminomas or normal tissue." (PMID 35454102, 2022). "Recently, this epigenetic signature was also considered as a potential biomarker for testicular cancer detection and differential diagnosis, since XIST 5’ demethylation levels are significantly higher in seminomas than in non-seminomas or normal testis." (PMID 33767982, 2021). "The DPPA3 and XIST genes were hypermethylated in LT-PTCs as compared to d0-PTCs and seminomas, MGMT displayed a variable DNA methylation pattern between and within groups and the KIT promoter was stably hypomethylated in all groups including seminomas." (PMID 32176716, 2020). "Furthermore, seminomas exhibited a strong positive correlation between XIST expression and replication stress scores (R = 0.47, P = 1.9e-04), which was absent in non-seminomas." (PMID 40568177, 2025). "More recently, XIST expression and the XIST-promoter demethylation status have been proposed as tissue biomarkers for TGCTs, which could discriminate between seminomas and non-seminomatous tumors." (PMID 34440480, 2021).
liver cancer (7 papers, 2019 to 2024). An epithelial or non-epithelial malignant neoplasm that arises from the liver. "Excessive miR 372 promotes metastasis of oral and liver cancers, but the role of XIST in PCa is rarely studied." (PMID 31467637, 2019). "Moreover, XIST acted as an upregulated lncRNA in liver cancer to promote liver cancer cell growth and metastasis." (PMID 35899235, 2022). "Importantly, the elevation in miR-497-5p may contribute to the XIST-mediated inhibition of liver cancer cell growth." (PMID 31384173, 2019).
lung adenocarcinoma (7 papers, 2018 to 2026). A carcinoma that arises from the lung and is characterized by the presence of malignant glandular epithelial cells. "Although sequence based computational analyses suggested that XIST has potential to interact with 864 miRNA species, only 13 miRNA-mRNA pairs found empirical evidence for regulation by XIST as ceRNA in the lung adenocarcinoma cell lines." (PMID 41601966, 2026). "Unsurprisingly, in lung adenocarcinoma sequencing data, XIST was observed to be expressed at higher levels in female tumours when compared to male tumours (n = 235) (Student’s t-test, p<0.0001)." (PMID 31419261, 2019). "While XIST expression is expected in all female somatic cells, we chose to interrogate lung adenocarcinoma (LUAD)." (PMID 31419261, 2019). "Serum EV-miR-21-5p, miR-486-3p, MEG3 and XIST levels may correlate with disease progression and treatment response in patients with ALK-translocated lung adenocarcinoma prescribed ALK-TKI treatment." (PMID 30658414, 2019).
Obesity (7 papers, 2021 to 2024). Accumulation of substantial excess body fat. "Asthma is associated with sex hormone levels and obesity, and some published researches revealed that XIST is involved in regulating these biological processes." (PMID 39346946, 2024). "Considering the well-established association between obesity and PCOS, the potential effects of the XIST- hsa-miR-146a-5p- PLEK axis on PCOS characteristics merit further investigation." (PMID 38486041, 2024). "To further explore the role of XIST in HFD induced obesity, we overexpressed XIST by plasmid injection via tale vein in male mice." (PMID 35062859, 2022). "In vivo experiments confirmed that XIST overexpression exhibited protection from HFD induced obesity and improved adipose tissue function." (PMID 35062859, 2022). "In vivo, XIST overexpression prevents high-fat diet induced obesity and improves metabolic dysorder in male mice." (PMID 35062859, 2022). "Our results suggest that XIST combats obesity through BAT activation at least partly by combination with transcription factor C/EBPα." (PMID 35062859, 2022). "X inactive specific transcript (XIST) is a long-stranded non-coding RNA that was significantly upregulated in ROHHAD samples and notably a recent report has described a role for XIST in human adipocyte differentiation and in preventing high fat diet induced obesity in mice." (PMID 37456561, 2023). "In the same study, the results indicate that XIST acts through direct binding to C/EBPα and BAT activation, consequently combating high-fat diet-induced obesity." (PMID 36386829, 2022).
testicular germ cell tumor (7 papers, 2011 to 2021). A germ cell tumor arising from the testis. "Of the 10 samples labeled male but classified female, there were 3 testes-related tumor cell lines with strong XIST expression in agreement with a previous report of testicular germ cell tumors expressing XIST35." (PMID 27857184, 2016). "In 1997 Looijenga and colleagues demonstrated how XIST expression is reactivated in testicular germ cell tumors (TGCT) following the acquisition of supernumerical X chromosomes." (PMID 33767982, 2021). "XIST expression is present in human testicular germ cell tumors, which is unusual considering that XIST is not normally expressed in male cells." (PMID 24212802, 2011).
acute kidney injury (6 papers, 2019 to 2024). Sudden and sustained deterioration of the kidney function characterized by decreased glomerular filtration rate, increased serum creatinine or oliguria. "In these studies, XIST knockdown was found to be protective of LPS-induced apoptosis and inflammation; acute lung injury; acute kidney injury; or myocardial ischemia reperfusion injury." (PMID 39198331, 2024). "Silencing of XIST ameliorates acute kidney injury by decreasing miR-142-5p and enhancing PDCD4 expression." (PMID 33299380, 2020). "XIST silencing reduces the levels of TNF-α and IL-6 in a rat acute kidney injury model caused by I/R." (PMID 33299380, 2020).
esophageal squamous cell carcinoma (6 papers, 2017 to 2024). Esophageal squamous cell carcinoma (ESCC) is a type of esophageal carcinoma (EC) that can affect any part of the esophagus, but is usually located in the upper or middle third. "The biological roles as well as the underlying mechanisms of XIST in esophageal squamous cell carcinoma remained yet to be solved." (PMID 29100288, 2017). "For instance, m6A modification is required for XIST-mediated gene suppression and MALAT1-induced cell migration and proliferation of esophageal squamous-cell carcinoma (ESCC) cells." (PMID 39497033, 2024). "It is noteworthy that, in esophageal squamous cell carcinoma (ESCC), XIST leads to increased levels of the enhancer of zeste homolog 2 (EZH2) by sequestering miR-101." (PMID 35804851, 2022).
osteoarthritis (6 papers, 2019 to 2025). A noninflammatory degenerative joint disease occurring chiefly in older persons, characterized by degeneration of the articular cartilage, hypertrophy of bone at the margins and changes in the synovial membrane. "And, lncRNA XIST was enhanced in osteoarthritis tissues, and XIST decreased with chondrogenic differentiation of BMSCs." (PMID 38167456, 2024). "In addition, we identified several non-coding RNAs associated with osteoarthritis, such as lncRNA OIP5-AS1 and lncRNA XIST." (PMID 40420260, 2025). "In conclusion, lncRNA XIST regulates progression of osteoarthritis." (PMID 37779916, 2023). "In addition, it is confirmed that lncRNA XIST can participate in the regulation of the toxic effect of M1 macrophages on chondrocytes in osteoarthritis." (PMID 35109760, 2022). "Studies have demonstrated that XIST could modulate proliferation and apoptosis in osteoarthritis chondrocytes." (PMID 31384173, 2019). "Interestingly, lncRNA XIST interacted with miR-150–5p and affected monocyte adherence, suggesting that lncRNA XIST might be useful for osteoarthritis treatment." (PMID 37779916, 2023). "Kaempferol reduced the functions of lncRNA XIST and miR-130a/STAT3 on ECM degradation and inflammation in osteoarthritis." (PMID 37779916, 2023).
osteoporosis (6 papers, 2019 to 2025). A condition of reduced bone mass, with decreased cortical thickness and a decrease in the number and size of the trabeculae of cancellous bone (but normal chemical composition), resulting in increased fracture incidence. "XIST has been implicated in promoting osteoporosis by inhibiting the differentiation of BMSCs." (PMID 40248073, 2025). "A study identified XIST upregulation in patients' serum, underscoring the difficulties in diagnosing osteoporosis through lncRNAs in plasma or serum." (PMID 41158629, 2025). "In future, we will establish a model of osteoporosis with ovariectomized rats, to study the effect of XIST/miR-29b-3p/NNMT signal axis on OP." (PMID 34486487, 2021). "In addition, study has reported that knockdown of RBM15 and RBM15B impairs XIST-mediated gene silencing, which influences osteoblast differentiation in osteoporosis." (PMID 36967763, 2023). "In mouse model, XIST alleviates osteoporosis induced by accumulation of iron." (PMID 34486487, 2021).
pneumonia (6 papers, 2019 to 2024). An acute, acute and chronic, or chronic inflammation focally or diffusely affecting the lung parenchyma, caused by an infection in one or both of the lungs (by bacteria, viruses, fungi, or mycoplasma.). "XIST overexpression in the serum of acute pneumonia patients has been reported, showing its relevance in immune response." (PMID 39198331, 2024). "In our work, inspired by these studies, we aimed to detect the role of XIST in LPS-stimulated pneumonia in WI-38 cells, as well as determine a novel XIST/miR-30b-5p axis regulating TLR4/NF-κB signaling pathway." (PMID 33817304, 2021). "The expression level of XIST was abundantly increased, but that of miR-30b-5p was significantly decreased in the serum from patients with pneumonia compared to the controls." (PMID 33817304, 2021). "This outcome suggested a potential role of XIST and miR-30b-5p in pathogenesis of pneumonia, as well as a potential interplay between both genes." (PMID 33817304, 2021). "Down-regulation of miR-370-3p reverses the promoting impact of lncRNA XIST knockdown on cell viability as well as the suppressive effects of XIST knockdown on the inflammatory response and apoptosis in an LPS-induced cell model of pneumonia." (PMID 34301223, 2021). "For instance, lncRNA XIST is robustly increased in the serum of patients with acute‐stage pneumonia and LPS‐induced human lung fibroblasts cells." (PMID 34114724, 2021). "In multiple pathophysiological process, XIST had been reported to be involved in the occurrence of disease, including human cancers, diabetes mellitus and pneumonia." (PMID 34114724, 2021). "Here, we observed that XIST expression was significantly upregulated in the serum of patients with pneumonia and LPS-treated WI-38 cells." (PMID 33817304, 2021). "In this study, we’ve examined expression of XIST and miR-30b-5p in the serum of patients with pneumonia." (PMID 33817304, 2021). "Next, Spearman's correlation analysis proved that XIST expression was positively while miR‐370‐3p expression was inversely correlated with TLR4 expression in acute‐stage pneumonia patients." (PMID 31066476, 2019). "The results showed that XIST expression was robustly increased in serum of patients with acute‐stage pneumonia and LPS‐induced WI‐38 human lung fibroblasts cells." (PMID 31066476, 2019). "Moreover, lncRNA XIST significantly increased in the serum from patients with acute pneumonia and in LPS-induced human lung fibroblasts of WI-38, playing a regulatory role as a ceRNA." (PMID 36429069, 2022). "Moreover, there was an inverse correlation between XIST and miR-30b-5p expression in patients with pneumonia (Spearman’s rank correlation analysis, r = 0.5698, P < 0.001)." (PMID 33817304, 2021). "These outcomes showed that LPS could induce cell apoptosis and inflammation in WI-38 cells, and XIST and miR-30b-5p were abnormally expressed in patients with pneumonia and LPS-treated WI-38 cells." (PMID 33817304, 2021). "Unfortunately, to date, the role of XIST in the inflammatory response in pneumonia remains largely unknown." (PMID 33817304, 2021). "In conclusion, we showed that XIST was upregulated in human pneumonia, and its knockdown could suppress the inflammatory injury in human lung fibroblast cells in vitro induced by LPS." (PMID 33817304, 2021). "Suppression of miR-370-3p eliminates the promoting impact of lncRNA XIST knockdown on cell viability as well as the inhibitory effects of XIST knockdown on the inflammation response and apoptosis in an LPS-induced cell model of pneumonia." (PMID 34301223, 2021). "In this study, XIST was detected highly expressed in serum of acute‐stage pneumonia." (PMID 31066476, 2019). "Above all, it is worth exploring whether XIST is able to interact with miR‐370‐3p thus playing a regulatory role in pneumonia." (PMID 31066476, 2019).
pneumonia (continued). "This study may supply novel clues for understanding the role of XIST in pneumonia progression and offer strategies for therapeutic approach to acute stage of pneumonia." (PMID 31066476, 2019). "Our study demonstrated that XIST was highly expressed in patients with acute stage of pneumonia." (PMID 31066476, 2019). "In conclusion, this study firstly indicated that XIST was increased in serum of patients with acute‐stage pneumonia and LPS‐injured WI‐38 cells; downregulation of XIST attenuated LPS‐induced apoptosis and inflammation in WI‐38 cells via modulating miR‐370‐3p/TLR4 axis." (PMID 31066476, 2019). "Therefore, CCL16 was a potent candidate for the target of XIST/miR-30b-5p axis in pneumonia." (PMID 33817304, 2021). "Thus, we put forward a hypothesis that there might be an interaction between XIST and miR-30b-5p in pneumonia." (PMID 33817304, 2021). "Hence, we speculated that implying XIST might play a potential role in regulating acute pneumonia development." (PMID 31066476, 2019). "Here, we provide the first evidence for the regulatory impact of XIST through modulating miR‐370‐3p/TLR4 axis in pneumonia, thus providing new idea for pneumonia diagnosis and treatment." (PMID 31066476, 2019). "Taken together, both the investigations suggested a protective role of XIST knockdown in LPS-induced inflammatory injury in WI-38 cells via sponging miRNAs, TLR4, and NF-κB pathways, thereby providing a novel target for the treatment of pneumonia." (PMID 33817304, 2021). "Expression of XIST and CCL16 was upregulated in the serum of patients with pneumonia and LPS-induced WI-38 cells, respectively; silencing XIST and CCL16 could suppress LPS-induced apoptosis and inflammation in WI-38 cells, and this protection was abolished by miR-30b-5p downregulation." (PMID 33817304, 2021). "Taken together, XIST may be involved in progression of cell inflammatory response, and XIST/miR‐370‐3p/TLR4 axis thus may shed light on the development of novel therapeutics to the treatment of acute stage of pneumonia." (PMID 31066476, 2019). "Moreover, the serum miR‐370‐3p expression in acute‐stage pneumonia patients was significantly decreased compared with healthy control, and the level of XIST and miR‐370‐3p exhibited a dramatically negative correlation confirmed by Spearman's correlation analysis." (PMID 31066476, 2019).